LINC02472 (long independently transcribed non-coding RNA 2472)
Gene: Long non-coding RNA gene on chromosome 4 (29,214,253 to 29,291,886, forward strand). Ensembl gene ENSG00000248338.
Diseases named in the same sentence as LINC02472 in open-access papers:
LINC02472 is named in the same sentence as 1 disease in open-access papers, as found by Europe PMC text mining. Sharing a sentence is not in itself a finding about the gene and the disease. The quoted sentences say what the papers report.
gastric cancer (1 paper, 2023). A primary or metastatic malignant neoplasm involving the stomach. "In this study, mGWAS-based studies localized four non-coding RNAs associated with gastric cancer prognosis, namely, MIR202HG (MIR202 host gene), MIR378D1, LINC02472, and LINC02310." (PMID 37894938, 2023).